CRH (corticotropin releasing hormone)
Diseases named in the same sentence as CRH in open-access papers (continued):
Sharing a sentence is not in itself a finding about the gene and the disease.
enteritis (2 papers, 2021 to 2022). Inflammation of the small intestine. "Referring to these studies, CRH-R2 antagonists reversed the CRH-induced increase in jejunal motility and colonic permeability and prevented C. difficile toxin A-induced enteritis as well as ischemia-induced hemorrhagic intestinal lesions, bacterial invasion, and macrophage inflammatory phenotype." (PMID 35275963, 2022). "Under stress (water-avoidance stress) conditions, mice developed enteritis due to inhibition of epithelial NLRP6 expression by the elevated corticotropin-releasing hormone (CRH), while PPARγ agonist rosiglitazone induced NLRP6 expression, and reversed intestinal inflammation." (PMID 33717162, 2021).
heart failure (2 papers, 2022 to 2026). Inability of the heart to pump blood at an adequate rate to meet tissue metabolic requirements. "An autocrine-paracrine CRH amplification loop sustains chronic coronary microvascular inflammation, contributing to heart failure with preserved ejection fraction (HFpEF) and MC activation disease (MCAD)-related cardiovascular manifestations." (PMID 42193398, 2026). "Corticotropin-releasing hormone has been reported to enhance the excitability of hypothalamic sympathetic nerves in heart failure." (PMID 36172573, 2022). "The expression of CRH in PVN of rats with ischemia-induced heart failure is elevated with the increased expression of pro-inflammatory cytokines and pro-inflammatory genes, even up to two times." (PMID 36172573, 2022).
hyperthyroidism (2 papers, 2012 to 2023). Overactivity of the thyroid gland resulting in overproduction of thyroid hormone and increased metabolic rate. "Studies have shown that corticotropin releasing hormone can affect the degree of hyperthyroidism." (PMID 37876543, 2023). "Studies have proposed that long-term chronic stress could cause hyperthyroidism of the HPA, that increased level of corticotropin-releasing factor (CRH), adrenocorticotropic hormone (ACTH), and corticosterone (CORT), which led to excessive expression of glucocorticoid receptor (GR) of HPA." (PMID 23008744, 2012).
ischemia (2 papers, 2021 to 2022). A hypoperfusion of the BLOOD through an organ or tissue caused by a PATHOLOGIC CONSTRICTION or obstruction of its BLOOD VESSELS, or an absence of BLOOD CIRCULATION. "More specific to ischemia, corticotropin-releasing hormone knockdown restricted to the hypothalamus led to decreased plasma CORT concentration and more EPM, OFT, and light-dark box exploration, while the opposite has been noted upon CRH infusion into the NAcS prior to EPM and OFT." (PMID 35058756, 2021).
Lewy body disease (2 papers, 2024 to 2025). "Corticotropin-releasing hormone is decreased in Lewy body disease and other APs and correlated with CI and inflammation in αSyn-positive disorders." (PMID 39997046, 2025). "CRH was decreased in de novo SAA+ Lewy body disease (patients who were not under dopaminergic medication) to a similar extent as in the SAA+ Lewy body disease group (P = 1.4e−03, AUC = 0.77)." (PMID 39605973, 2024). "We aimed to confirm the link of CRH in Lewy body disease and elucidate its role as a biomarker in the disease, particularly its association with cognition, motor symptoms, psychiatric symptoms and CSF inflammatory markers." (PMID 39605973, 2024). "In BioFINDER-2, CSF CRH was reduced in SAA+ Lewy body disease and SAA+ CUI individuals compared with SAA− CUI (P = 3.3e−05, AUC = 0.79; P = 2.9e−03, AUC = 0.80)." (PMID 39605973, 2024). "CRH was downregulated in αSyn positive Lewy body disease, αSyn positive controls and in all atypical PS compared with αSyn negative controls (P = 3.3e−05, P = 3.1e−10, P = 2.9e−03)." (PMID 39605973, 2024). "We confirm CRH as a candidate biomarker for Lewy body disease and show novel data for its utility in atypical PS." (PMID 39605973, 2024). "To elucidate what clinical impact CRH may have in Lewy body disease, we assessed its relationship with psychiatric and cognitive measures." (PMID 39605973, 2024). "Reductions in CRH in Lewy body disease and other PS suggest this decrease may relate to dopaminergic degeneration instead of αSyn pathology." (PMID 39605973, 2024). "Notably, atypical PS individuals [PSP = 25 (SAA− = 23; SAA+ = 2); MSA = 12 (SAA− = 12; SAA+ = 0)] showed a stronger downregulation in CRH than the Lewy body disease group, when compared with SAA− CUI (P = 3.1e−10, AUC = 0.85)." (PMID 39605973, 2024). "Since this downregulation seems to be only partly affected by the presence of αSyn, we propose the decrease of CRH levels in Lewy body disease and atypical PS could be related to dopaminergic dysfunction instead." (PMID 39605973, 2024). "CRH was decreased in SAA+ Lewy body disease compared with SAA− CUI (P = 0.02, AUC = 0.65)." (PMID 39605973, 2024). "Corticotropin-releasing hormone (CRH) was proposed as a biomarker for Lewy body disease." (PMID 39605973, 2024). "We propose that, given that CRH levels are decreased in Lewy body disease patients and SAA+ CUI, in comparison to SAA− CUI, αSyn might be responsible for the decrease in CRH levels." (PMID 39605973, 2024). "Furthermore, we observed that dopaminergic medication had no impact on the levels of CRH, as seen in the de novo SAA+ Lewy body disease group." (PMID 39605973, 2024).
mastitis (2 papers, 2017 to 2021). Inflammation of breast tissue during lactation or postpartum due to an obstructed duct or infection. "Other studies described that inflammatory mediators induced by mastitis, increase the release of CRH and thereby activate the HPA-axis." (PMID 33803996, 2021).
mastocytosis (2 papers, 2023 to 2024). A clonal myeloproliferative neoplasm characterized by the proliferation and accumulation of neoplastic mast cells in one or multiple organs or organ systems. "A clinical report showed that patients with psychological stress have high levels of CRH in the serum and mastocytosis conditions." (PMID 39336134, 2024). "Additionally, MCs were reported to secrete CRH and express CRH receptors, indicating the role of CRH in stress-related symptoms of mastocytosis." (PMID 37372988, 2023).
metastatic melanoma (2 papers, 2021 to 2025). A melanoma that has spread from its primary site to another anatomic site. "For CRH expression, a significant difference between female and male metastatic melanomas was evaluated." (PMID 40917468, 2025). "Survival data of male and female patients with metastatic melanoma were correlated with CRH expression." (PMID 40917468, 2025). "Explaining the decreased survival of men with high CRH-expressing metastatic melanoma is not straightforward." (PMID 40917468, 2025).
migraine (2 papers, 2016 to 2021). "In turn, MCs react to various neuronal stimuli, such as substance P (SP), CGRP, corticotropin-releasing hormone (CRH), histamine, many of which are also associated with migraine pathophysiology." (PMID 27148260, 2016).
multiple sclerosis (2 papers, 2013 to 2022). A progressive autoimmune disorder affecting the central nervous system resulting in demyelination. "A hyperactive HPA axis has often been reported in multiple sclerosis (MS): in post mortem studies enlarged adrenals as well as increased activity of corticotropin-releasing-hormone (CRH) producing cells within the hypothalamus have been found." (PMID 23613736, 2013).
myocardial ischemia (2 papers, 2018 to 2024). A disorder of cardiac function caused by insufficient blood flow to the muscle tissue of the heart. "In future research, further experimentation can be done to test the influence of LXNX on CRH and NPPA pathway by in vitro and in vivo experiments on mice with myocardial ischemia." (PMID 29867541, 2018).
ovarian neoplasm (2 papers, 2007 to 2016). A benign, borderline, or malignant neoplasm involving the ovary. "Therefore, CRH may act in a paracrine and/or autocrine way to modulate various functions of ovarian tumour cells." (PMID 17667919, 2007). "In summary, we found that CRH, its receptors CRHR1 and CRHR2, and the proapoptotic molecule FasL are produced by human ovarian tumour cells in situ." (PMID 17667919, 2007). "Since a large proportion of ovarian tumours were found to express CRHR1 (70.2%), secretion of CRH might considerably improve tumour's resistance to immune attack and thus favour its survival and progression." (PMID 17667919, 2007).
panhypopituitarism (2 papers, 2008 to 2020). Insufficient production of all the anterior pituitary hormones. "Load tests were conducted using four hypothalamic hormones: LH-releasing hormone (100 μg), GH-releasing hormone (100 μg), corticotropin-releasing hormone (CRH, 100 μg), and thyrotropin-releasing hormone (TRH, 250 μg) in order to confirm the diagnosis of panhypopituitarism." (PMID 33019443, 2020).
prostate carcinoma (2 papers, 2010 to 2022). A carcinoma that arises from epithelial cells of the prostate gland. "Interestingly, isolated CRH production from prostate cancer comprises 14% of the cases and yet it is an extremely rare source of ectopic ACTH (1-3%).There are single reports of sellar choristoma and gangliocytoma with isolated CRH production." (PMID 20807418, 2010).
Ventriculomegaly (2 papers, 2021 to 2025). An increase in size of the ventricular system of the brain. "We found significant and consistent decrements in CRH level associated with ambient PM2.5 exposure, which has been previously associated with placental inflammation and ventriculomegaly in premature infants." (PMID 40151202, 2025).
viral infection (2 papers, 2011 to 2017). "In response to stressors, such as dehydration, heat shock, or viral infection, corticotropin-releasing hormone (CRH) is secreted from the hypothalamus, which facilitates the secretion of adrenocorticotropic hormone (ACTH) in the pituitary." (PMID 28379983, 2017). "In CRH-knockout mice viral infection leads to an ACTH independent corticosterone response, which is associated with significantly higher IL-6 plasma concentrations compared to WT mice." (PMID 21466684, 2011).
adrenal pheochromocytoma (1 paper, 2018). "In this case, a pre-existing tumor, chronological dexamethasone administration, and clinical symptoms and signs suggested that dexamethasone might induce CRH gene expression and/or secretion in the adrenal pheochromocytoma, thereby may provoke ectopic CRH syndrome." (PMID 29921267, 2018).
alcohol addiction (1 paper, 2025). "CRH seems to be involved in all stages of alcohol addiction." (PMID 41301894, 2025). "Targeting neuropeptides such as CRH and AVP, and their receptors involved in both binge drinking and social behavior, may prevent repeated cycles of binge drinking and hangover from spiraling into alcohol addiction and, ultimately, social isolation." (PMID 41301894, 2025).
Autoimmunity (1 paper, 2024). The occurrence of an immune reaction against the organism's own cells or tissues. "While during acute stress, leukocyte distribution and function were shaped in distinct brain regions, corticotropin-releasing hormone neuron-mediated leukocyte shifts protected against the acquisition of autoimmunity, hence calibrating the immune system’s response to physical threats." (PMID 39268034, 2024).
bladder (1 paper, 2019). "Our findings suggest the CRH pathway may be involved in the mechanism of neurogenic inflammation in IC/BPS bladder." (PMID 31844086, 2019).
bone cancer (1 paper, 2019). A primary or metastatic malignant neoplasm affecting the bone or articular cartilage. "Previous studies showed that CRH had an important function on the modulation of pain resulted from bone cancer or inflammatory nociceptive stimuli and acted on important brain structures in pain regulatory." (PMID 31213976, 2019).
brain tumors (1 paper, 2015). "Moreover, it has been proposed that metastatic brain tumors can be promoted by stress (unavoidable in patients with cancer) which activates brain MCs to disrupt the BBB via the CRH pathway." (PMID 26377554, 2015).
cerebral edema (1 paper, 2021). "Furthermore, studies in a rat model of cerebral edema showed that the activation of TLR4 and corticotropin-releasing hormone (CRH)/CRH receptor 1 (CRHR1) signaling upregulated AQP4 and water permeability in the brain during short hypoxia." (PMID 33673336, 2021).
cholestasis (1 paper, 2025). Impairment of the bile flow caused by obstruction within the liver, or outside the liver in the bile duct system. "Broadly expressed: hypothalamus (CRH neurons), pituitary, adrenal, liver, immune cells; bile acids can access hypothalamus in cholestasis." (PMID 41465592, 2025).
chronic rhinosinusitis (1 paper, 2021). Chronic form of sinusitis. "As these findings would be of clinical relevance under, for example, conditions of stress-aggravated nasal allergy or chronic rhinosinusitis, we evaluated whether CRH upregulates its own receptor, sensitizing hM-MCs in a positive feedback loop to further CRH stimulation." (PMID 33803422, 2021).
clear cell renal cell carcinoma (1 paper, 2022). "Urocortin (UCN), belonging to the corticotropin-releasing hormone (CRH) family, is involved in an immune-related signature in the clear cell renal cell carcinoma (ccRCC or KIRC)." (PMID 35831825, 2022).
cocaine abuse (1 paper, 2020). Disorders related or resulting from use of cocaine. "Nevertheless, some studies seem to suggest that abnormalities in diurnal ACTH and cortisol levels or in pituitary response to corticotropin-releasing hormone (CRH) that may develop during cocaine abuse appear to normalize during extended abstinence from cocaine." (PMID 32992573, 2020).
diabetes insipidus (1 paper, 2023). A disorder characterized by excretion of large amounts of urine, accompanied by excessive thirst. "Excessive GABAergic inhibition in the hypothalamus could suppress the release of corticotropin releasing hormone (CRH) and antidiuretic hormone (ADH), resulting in cortisol deficiency with diabetes insipidus." (PMID 37978513, 2023).
E. coli infection (1 paper, 2015). "If deficiency of PKR can hyper-induce CRH at inflammatory sites during the E. coli infection, such CRH may potentially spill over into the bloodstream and upregulate corticosterone." (PMID 26585788, 2015). "A delay in the CRH response in PKR−/− mice suggests that endogenous CRH signaling at an early time after the E. coli infection is required for normal sickness development." (PMID 26585788, 2015). "However, at 48 h after E. coli infection, there was a significant elevation of CRH in PKR−/− mice but not in WT mice." (PMID 26585788, 2015).
gastric ulcer (1 paper, 2018). An ulcerated lesion in the mucosal surface of the stomach. "Microinjection of neurotransmitters or neuropeptides including γ-aminobutyric acid, β-endorphin, dopamine, thyrotropin-releasing hormone, and CRH into the CEA results in the attenuation or aggravation of stress-induced gastric ulcers." (PMID 30171524, 2018). "The exact role that the CEA CRH neurons play in stress-induced gastric ulceration deserves further investigation." (PMID 30171524, 2018). "Interestingly, our data suggested a possible correlation between stress-induced gastric ulceration and the activation of CEA CRH neurons." (PMID 30171524, 2018).
hemochromatosis (1 paper, 2024). A disorder of iron metabolism characterized by a triad of HEMOSIDEROSIS; LIVER CIRRHOSIS; and DIABETES MELLITUS. "AI in bThal results from iron deposition/secondary hemochromatosis in the adrenal cortex (primary AI) or the pituitary gland (secondary or central AI; the latter term usually also includes cases of hypothalamic causes of AI caused by lack of CRH production)." (PMID 39459358, 2024).
Hepatic steatosis (1 paper, 2026). Steatosis is a term used to denote lipid accumulation within hepatocytes. "Pseudorabies virus retrograde tracing and neuronal circuit interrogation further showed that projection from the medial central amygdaloid nucleus (CeM) to paraventricular hypothalamic corticotropin-releasing hormone (CRHPVH) neurons mediated stress induced hepatic steatosis." (PMID 41608627, 2026).
hepatoma (1 paper, 2008). "TPA, as well as Fsk increases the CRH secretion from hepatoma-derived, homologous NPLC-KC cells, or from dissociated hypothalamic primary culture." (PMID 19787076, 2008). "Also, the endogenous CRH mRNA expression is induced by IL-1β along with the induction of c-fos, c-jun, and GR gene expression in human hepatoma NPLC-KC cells." (PMID 19787076, 2008).
insulinoma (1 paper, 2013). "In the Min6 insulinoma cells the pattern changed, the BoT-Staple-EGF was as efficient as Bitox whereas CNTF and CRH moieties were less effective." (PMID 23638840, 2013).
internalizing disorder (1 paper, 2022). A type of mental or behavioral disorder, typically in children and young adults, with symptoms including depression, anxiety and withdrawal. "Future studies should collect multiple stress markers (e.g., cortisol, corticotropin-releasing hormone) to determine relationships between cytokines levels and stress response markers within pediatric internalizing disorders." (PMID 35880170, 2022).
Intrahepatic cholestasis of pregnancy (1 paper, 2017). "A clinical study on the expression of CRH in patients with intrahepatic cholestasis of pregnancy (ICP) after ursodeoxycholic acid (UDCA) treatment determined that CRH was significantly down-regulated in patients with ICP and that UDCA treatment resulted in an attenuation of serum CRH concentrations." (PMID 29125588, 2017).
kidney cancer (1 paper, 2016). Primary or metastatic malignant neoplasm involving the kidney. "We describe for the first time tumor specific epigenetic silencing of CRHBP and statistical association with aggressive tumors thus suggesting the CRH system to contribute to the development of kidney cancer." (PMID 27695045, 2016).
kidney injury (1 paper, 2023). Trauma to the kidney. "While investigating determinants of serum apelin-13 level by multiple linear regression analysis in two different models, CRH, SAPS II, serum sodium, potassium, and the presence of kidney injury were independent predictors." (PMID 37510916, 2023).
kidney tumors (1 paper, 2016). "While these studies identify members of the CRH system to participate in skin and prostatic tumor model cell lines, our preliminary functional analyses provide evidence that the CRH system may also be of relevance for kidney tumors cells." (PMID 27695045, 2016).
lichen (1 paper, 2024). "In the present retrospective study, we investigated the immunohistochemical expression of CRH, UCN, FAS-L and of their receptors CRHR1, CRHR2 and FAS, on paraffin-embedded tissue samples from patients diagnosed with lichen (sclerosus or planus), VIN or VSCC." (PMID 37382757, 2024). "Similarly, CRH expression was higher in VIN cases, compared to lichen cases (U = 77.5, Z = − 4.8, p < 0.001 two tailed)." (PMID 37382757, 2024). "Immunohistochemical expression of CRH, urocortin (UCN), FasL and their receptors CRHR1, CRHR2 and Fas was studied in vulvar tissue sections obtained from patients with histologically confirmed diagnosis of lichen, vulvar intraepithelial neoplasia (VIN) and vulvar squamous cell carcinoma (VSCC)." (PMID 37382757, 2024).
lichen sclerosus (1 paper, 2024). "It was clearly shown that CRH expression is gradually increased during the transition from lichen sclerosus to VIN and vulvar cancer, thus implying a possible role for CRH and its downstream pathways in local modulations towards an anti-apoptotic cellular scheme." (PMID 37382757, 2024).
lung adenocarcinoma (1 paper, 2024). A carcinoma that arises from the lung and is characterized by the presence of malignant glandular epithelial cells. "POU6F1 is associated with corticotropin-releasing hormone expression regulation, neuroplasticity and the proliferation of lung adenocarcinoma." (PMID 39020437, 2024).